PPARA (peroxisome proliferator activated receptor alpha)
Diseases named in the same sentence as PPARA in open-access papers (continued):
Sharing a sentence is not in itself a finding about the gene and the disease.
Cerebral ischemia (continued). "To examine whether the inhibitory effect of OEA on microglia/macrophage M1 polarization was specifically mediated by PPARα signaling, we further performed focal cerebral ischemia in PPARα-knock-out (KO) mice." (PMID 37111378, 2023). "Thus, in this study, the effects of PPARα on astrocyte activation and autophagic flux after cerebral ischemia were evaluated." (PMID 36979952, 2023). "In summary, this study identifies the role of PPARα in inhibiting the inflammation activation of astrocytes during the chronic phase of cerebral ischemia, and provides a new insight into the importance of PPARα in regulating neuroinflammation, partially through an autophagic flux regulation." (PMID 36979952, 2023). "Furthermore, OLE activates the peroxisome proliferator-activated receptor (PPARα) in neurons and astrocytes, providing neuroprotection against noxious biological reactions that are induced following cerebral ischemia." (PMID 37626746, 2023). "We first observed the effect of PPARα on neurological function after brain ischemia." (PMID 36979952, 2023). "In addition, OEA treatment restored PPARα expression, inhibited astrocyte activation, and promoted autophagic flux in brain tissues at 14 d, after transient brain ischemia occurred in mice." (PMID 36979952, 2023). "Therefore, all these results indicate that the protection of PPARα activation is mediated by the restoration of autophagic flux after transient brain ischemia." (PMID 36979952, 2023). "In vivo as well as in vitro studies confirmed that preventive treatment, administration during the acute phase as well as therapeutic application of PPARα agonists such as fenofibrate could decrease brain damage after cerebral ischemia." (PMID 28603485, 2017). "Because EC loss and subsequent vasoregression contribute to neurodegeneration in cerebral ischemia, DR, peripheral neuropathy, and age-related neurodegenerative diseases, it is likely that PPARα-mediated vasoprotection contributes to the observed neuroprotective effects in these models." (PMID 25705219, 2015). "However, the effect of PPARα on other cells after brain ischemia, such as neurons and endothelial cells, remains relatively unknown." (PMID 36979952, 2023). "In the present study, we propose a novel mechanism for the PPARα-medicated inhibition of astrocyte inflammation activation by preserving the lysosome function and by restoring autophagic flux through the subsequent lysosomal degradation of autophagic vesicles after transient brain ischemia." (PMID 36979952, 2023). "However, whether and how PPARα mediates the astrocyte inflammatory transition after brain ischemia remains unknown." (PMID 36979952, 2023). "Although PPARα's beneficial effects upon the blood-brain barrier in cerebral ischemia are not fully understood, PPARα may also improve tight junction integrity in this model through mechanisms similar to that in intestinal permeability and HIV-induced cerebrovascular toxicity." (PMID 25705219, 2015). "Ours and others’ previous studies have shown that the PPARα agonist OEA and palmitoylethanolamide inhibit astrocyte activation and promote motor function recovery after cerebral ischemia." (PMID 36979952, 2023). "Further, several studies have also suggested that PPARα attenuates blood-brain barrier disruption in HIV-induced cerebrovascular toxicity and cerebral ischemia." (PMID 25705219, 2015). "Although the precise mechanism of the effect of PPARα on astrocyte autophagic flux after brain ischemia is not well understood, lysosomes in astrocytes may play an important role." (PMID 36979952, 2023).
non-small cell lung carcinoma (18 papers, 2011 to 2025). A group of at least three distinct histological types of lung cancer, including non-small cell squamous cell carcinoma, adenocarcinoma, and large cell carcinoma. "PPARα activation in vivo using Wy-14,643 or bezafibrate reduced non-small-cell lung cancer (NSCLC) growth through the inhibition of a proangiogenic epoxygenase." (PMID 35954274, 2022). "Interestingly, a previous study on cancer cachexia using a non-small cell lung cancer mouse model reported decreased PPARα nuclear localization and PPARα-dependent ketogenesis in the liver of mice that developed cancer cachexia." (PMID 38245529, 2024).
atopic dermatitis (17 papers, 2010 to 2026). "PPARα deficient-mice have been reported to exhibit exacerbated inflammation in a mouse model of atopic dermatitis, and the expression of PPARα is reduced in the lesional skin of atopic dermatitis." (PMID 27611371, 2016). "Eupatilin has been shown to promote the transcriptional activity and expression of peroxisome proliferator-activated receptor α (PPARα) in keratinocyte HaCaT cells and acts as an agonist of PPARα to ameliorate atopic dermatitis (AD) and restore the skin barrier function." (PMID 30886621, 2019). "Topical treatment regimen consisting of PPARα activator showed potent anti-inflammatory effects in murine models of atopic dermatitis and in irritant and allergic contact dermatitis, which were associated with reduction in pro-inflammatory cytokines TNF-α and IL-1α." (PMID 27611371, 2016). "Other studies investigated the role of PPARα in mouse model of atopic dermatitis." (PMID 21382489, 2011). "Furthermore, PPARα activation decreased epidermal production of inflammatory cytokines in both ovalbumin and oxazolone induced atopic dermatitis." (PMID 21382489, 2011). "With respect to PPARα, its expression has been found to be reduced in eczematous skin from patients with atopic dermatitis compared to skin from non-atopic donors." (PMID 36552866, 2022). "In the oxazolone induced atopic dermatitis model, the topical activation of PPARα by WY-14643 could normalize the structure of epidermis, significantly improved barrier function of the skin and increased stratum corneum hydration as well as reversed the immunologic abnormalities." (PMID 21382489, 2011).
Huntington disease (17 papers, 2015 to 2024). Huntington disease (HD) is a rare neurodegenerative disorder of the central nervous system characterized by unwanted choreatic movements, behavioral and psychiatric disturbances and dementia. "A similar finding was observed in regards to the neuroprotective effects of Rosi on Huntington’s disease which showed that PPARγ, but not PPARα, plays an important role on rescuing motor dysfunction." (PMID 25799429, 2015).
primary biliary cholangitis (17 papers, 2017 to 2025). Primary biliary cholangitis (PBC) is a chronic and slowly progressive cholestatic liver disease of autoimmune etiology characterized by injury of the intrahepatic bile ducts that may eventually lead to liver failure. "Fibrates, which are agonists of peroxisome proliferator-activated receptor alpha, have received increasing attention in the treatment of primary biliary cholangitis." (PMID 35880178, 2022). "Pemafibrate also provides more potent ALP reduction than the conventional PPARα agonist fenofibrate, and is expected to be a useful treatment option for primary biliary cholangitis." (PMID 33947390, 2021). "PPARα/γ dual agonists (e.g., glitazar) and PPARα/δ dual agonists (e.g., elafibranor) have been developed for clinical use in adults with primary biliary cholangitis, and pan-PPAR agonists are under Phase III clinical trials for nonalcoholic steatosis (e.g., lanifibranor, a PPARα/γ/δ agonist)." (PMID 35625650, 2022). "In the phase 3 study of “Bezafibrate in Combination with Ursodeoxycholic Acid in Primary Biliary Cirrhosis (BEZURSO; NCT01654731)” completed in December 2016, its dual actions on PPARα/δ were considered important for the improvement of biochemical measures, such as liver stiffness." (PMID 35563117, 2022). "First, we examined the recruitment of four coactivators to the PPARα/δ/γ-LBD by synthetic Glaxo–Wellcome (GW) series full agonists and approved PPARα/δ/γ-selective agonists: pemafibrate, seladelpar (approved for the treatment of primary biliary cholangitis in August 2024), and pioglitazone." (PMID 41465444, 2025).
endometriosis (16 papers, 2015 to 2026). The growth of functional endometrial tissue in anatomic sites outside the uterine body. "The present study assessed whether rapamycin, a senescence inhibitor, ameliorates endometriosis-associated infertility by upregulating peroxisome proliferator-activated receptor α (PPARα) and insulin-like growth factor-binding protein 2 (IGFBP2) expression." (PMID 41170754, 2026). "In summary, the results of the present study highlight that ROS-induced ovarian senescence contributed to endometriosis-related infertility, and rapamycin counteracted this process by activating the PPARα/IGFBP2 pathway." (PMID 41170754, 2026). "The findings of the present study revealed for the first time, to the best of our knowledge, that PPARα and IGFBP2 are downregulated in endometriosis-affected ovaries and are negatively associated with senescence." (PMID 41170754, 2026). "Based on the study results, negative regulation of the PPARα pathway seems to promote endometriosis progression and to hinder adequate vascularization which directly correlates with the level of inflammation at the endometriotic implantation site." (PMID 38690174, 2024). "The activation of PPARα was also described as a potential factor of recovery from endometriosis in both models." (PMID 38690174, 2024). "The activation of PPARα was also noted as a factor potentially contributing to recovery from endometriosis in both models." (PMID 34552688, 2021). "In our experiment, we observed an increased expression of PPARα in both rat endometriosis lesion and HEcESCs upon the treatment of resveratrol." (PMID 34552688, 2021). "Pharmacological modulation (such as PPARα agonists/antagonists) or conditional knockout models could elucidate whether targeting this pathway rescues ovarian function in endometriosis." (PMID 41170754, 2026). "In endometriosis, reduced PPARα/IGFBP2 signaling may exacerbate oxidative stress-induced ovarian damage." (PMID 41170754, 2026). "Rapamycin treatment increased PPARα and IGFBP2 expression in ovarian tissues, suggesting that its therapeutic effect on endometriosis-related infertility may involve the PPARα/IGFBP2 pathway by mitigating cellular senescence." (PMID 41170754, 2026). "In this study, PPARA was identified to be downstream of endometriosis." (PMID 39796277, 2025). "Similarly, resveratrol, another flavonoid, has been extensively studied for its role in regulating PPARα and PPARγ activity in endometriosis models." (PMID 39803270, 2025). "Only two study groups have, so far, investigated the role of PPARα in endometriosis." (PMID 38690174, 2024). "In the context of PPARα therapeutic targeting, the administration of resveratrol in endometriosis seemingly leads to the activation of PPARα which might potentially contribute to the recovery from this disease." (PMID 38690174, 2024). "Two studies have, so far, examined the role of PPARα in endometriosis." (PMID 38690174, 2024). "As such, the current article constitutes an up-to-date review comprehensive of the literature about the effects of the PPAR isoforms PPARα and PPARγ in endometriosis establishment and progression, alongside their potential as eventual anti-endometriotic treatment targets." (PMID 38690174, 2024). "In turn, the observed activation of peroxisome proliferator-activated receptor α (PPARα) may be a potential contributor to recovery from endometriosis." (PMID 37375677, 2023). "The present study demonstrated that elevated ROS in the peritoneal fluid of endometriosis mice contributed to ovarian senescence and impaired follicular development, whilst rapamycin treatment mitigated these effects by reducing oxidative stress and activating the PPARα/IGFBP2 pathway." (PMID 41170754, 2026). "This indicated that the expression of PPARα and IGFBP2 in the ovaries of endometriosis mice was significantly decreased, and treatment with rapamycin activated PPARα and IGFBP2 expression." (PMID 41170754, 2026).
endometriosis (continued). "From the results of this study, it remained unclear exactly how and to what extent PPARA and HLA-DQB1 contributed to the presence and severity of endometriosis." (PMID 39796277, 2025). "Peritoneal fluid from patients with endometriosis activated U937 cells which had been transiently transfected with a PPARα reporter, whereas it did not successfully activate PPARγ constructs." (PMID 38690174, 2024). "Therefore, the present study aimed to assess whether downregulation of the PPARα/IGFBP2 pathway in senescent ovarian tissue impairs follicular development, and whether rapamycin can restore fertility in endometriosis by modulating this signaling axis." (PMID 41170754, 2026).
fibrosis (16 papers, 2013 to 2024). the formation of excess fibrous connective tissue in an organ or tissue in a reparative or reactive process. "Fenofibrate is known as an agonist of PPARα, and its inhibitory effect on bronchial, lung, subretinal, and liver fibrosis has been observed." (PMID 37175437, 2023). "PPARα involvement in the regulation of inflammation, hypertrophy, energy metabolism, ischemia/reperfusion injury, and cardiac fibrosis in hearts has been established in recent studies." (PMID 36291052, 2022). "PPARα had shown the protection in ameliorating cardiac fibrosis by inhibiting TGF-β signaling." (PMID 32963130, 2020). "In confirmation of our hypothesis, we show that specific CpGs within TGFβ1 (CpG2) and PDGFα (CpG3) are significantly more methylated in patients with mild fibrosis whereas PPARα (CpG3) and PPARδ (CpG2) show considerably less methylation in the same group." (PMID 25859289, 2015). "Interestingly, PPARα was recently shown to protect against liver ferroptosis and might further suppress pathological progression into liver pyroptosis-fibrosis-cirrhosis." (PMID 39086681, 2023). "In mice, reactivation of PPARα reduced STAT3 phosphorylation and expression of fibrotic markers implying that the observed PPARα downregulation not only contributes to lipid accumulation but also to cardiac fibrosis." (PMID 38892395, 2024).
Hepatitis (16 papers, 2016 to 2025). Inflammation of the liver. "Inhibiting miR-21 expression can also suppress a methionine-choline-deficient (MCD) diet-induced liver inflammation and fibrosis by recovering the function of PPARα, evidenced by loss of function of inhibitor of miR-21 in PPARα-deficient mice." (PMID 34299189, 2021). "PPARα exerts anti-inflammatory activity, for example, and PPARα agonists mediate a variety of effects on the immune response to reverse acute and chronic liver inflammation." (PMID 34359615, 2021). "The current study was thus aimed at understanding the impact of PPARα in the complex setting of T cell-mediated hepatitis." (PMID 29448959, 2018). "In addition, the fatty acid β-oxidation-related proteins CPT1, CPT2, ACOX1, and ACOX2 were also affected and downregulated by the downregulation of PPARα, resulting in the accumulation of lipids in cells and aggravation of the degree of hepatitis." (PMID 38139341, 2023). "Given the importance of cytokines to the development of ConA-induced hepatitis, it was hypothesized that the cytokine response would be impaired in PPARα−/− mice when compared to their wild type controls." (PMID 29448959, 2018). "The purpose of this study was to determine whether PPARα plays a role in T cell-mediated hepatitis induced by Concanavalin A (ConA)." (PMID 29448959, 2018). "Patients with T2DM can develop various complications, including fatty liver and liver inflammation, and dysfunction of hepatic lipid metabolism could be improved by activation of Cpt-1, Hmgcs2, and Pparα to enhance hepatic oxidation and the metabolism of adipose tissue." (PMID 35186190, 2022). "Furthermore, these data provide a mechanism by which PPARα may regulate ConA-induced T cell-mediated hepatitis." (PMID 29448959, 2018). "This aggravates development of MCD diet‐induced hepatitis potentially by decreasing FXR and PPARα signalling." (PMID 32141703, 2020). "After 18 weeks, HFD mice developed NASH like features with severe steato-hepatitis and fibrosis, increased hepatic content of triacylglycerol and cholesterol and expression of SREPB1c, FAS, ApoC2, PPARα and γ, α-SMA, α1 collagen and MCP1 mRNAs." (PMID 28202906, 2017).
hepatitis C (16 papers, 2009 to 2024). "Finally 6 genes (NCOR2, NR1H3, PPARA, IRF3, MAP2K3, and TLR6) were enriched in 3 immune-related pathways, including toll-like receptor signaling pathway, EB virus infection, and hepatitis C." (PMID 37845378, 2023). "This is because, for hepatitis C, inflammation is a contributing factor for carcinogenesis as compared to hepatitis B. It has been reported that HCV core results in carcinogenesis at a high rate by continuously activating PPARα." (PMID 24696843, 2014).
injury (16 papers, 2007 to 2025). Damage inflicted on the body as the direct or indirect result of an external force, with or without disruption of structural continuity. "PPARα activation with Wy-14,643 has been reported to suppress inflammation in mouse and human models of acute liver injury." (PMID 35203271, 2022). "In conclusion, novel mechanisms of a PPARα agonist were elucidated to attenuate BBB breakdown during traumatic brain injury in vitro." (PMID 28603485, 2017). "Consistently, PPARα activation reduces the anti-autophagic effects of miR-19a mimic and elevates LC3-II/LC3-I ratio and Beclin-1 expression in models of acute liver injury." (PMID 35203271, 2022).
chronic kidney disease (15 papers, 2012 to 2026). Impairment of the renal function secondary to chronic kidney damage persisting for three or more months. "Additionally, statins and PPARα activators may increase the risk of developing myopathy and rhabdomyolysis, which is greater in patients with chronic kidney disease (CKD)." (PMID 30736366, 2019). "The protective role of peroxisome proliferator-activated receptor α (PPARα) activation in nephrosis induced by fatty acids and chronic kidney disease (CKD) recently has been drawing great attention." (PMID 31979102, 2020). "Recently, genome‐wide transcriptomic analysis revealed decreased expression of PPARα and FAO‐related genes in the kidneys of patients with chronic kidney disease (CKD), underscoring the importance of maintaining renal FAO ability." (PMID 41460648, 2026). "Based on these facts, the activation of PPARα signaling and FAM in the kidney is presumed to suppress renal fibrosis and the progression of renal dysfunction in patients with chronic kidney disease (CKD)." (PMID 34207854, 2021). "TGFβ suppresses the PPARA’s expression in chronic kidney disease (CKD) patients with kidney fibrosis and our in vitro and in vivo studies showed that PPARA or PPARGC1A was down-regulated by zoledronate treatments." (PMID 28871336, 2018). "Because MsPGN is one of the significant factors leading to chronic kidney disease (CKD), the beneficial antinephritic effect of PPARα activation may provide a novel treatment strategy against CKD." (PMID 23125847, 2012).